WFDC21P (WAP four-disulfide core domain 21, pseudogene )
Synonyms: LNCDC; linc-DC; lnc-DC
Gene: Long non-coding RNA gene on chromosome 17 (60,083,560 to 60,091,985, reverse strand). Ensembl gene ENSG00000293515.
Diseases named in the same sentence as WFDC21P in open-access papers:
WFDC21P is named in the same sentence as 11 diseases in open-access papers, as found by Europe PMC text mining. Sharing a sentence is not in itself a finding about the gene and the disease. The quoted sentences say what the papers report.
gastric cancer (3 papers, 2022 to 2024). A primary or metastatic malignant neoplasm involving the stomach. "Right after, GEPIA database was used to verify the expression of WFDC21P in gastric cancer." (PMID 38528582, 2024). "Accordingly, we supposed that WFDC21P may also bind to proteins to regulate gastric cancer malignant behaviors." (PMID 38528582, 2024).
lung carcinoma (2 papers, 2021 to 2022). "In this study, we found that miR-4293 downregulates the degradation of WFDC21P by directly mediating DCP2, which plays important role in the tumorigenesis of lung carcinoma." (PMID 34301920, 2021). "Therefore, we assumed that WFDC21P may be regulated by DCP2, and is involved in the pathogenesis of lung cancer." (PMID 34301920, 2021).
tumor (3 papers, 2020 to 2025). "Other research shows that miR-4293 regulating WFDC21P through downregulate DCP-2 while miR-4293 promotes tumor cell proliferation and metastasis but suppresses apoptosis." (PMID 40895564, 2025). "We further investigated whether WFDC21P regulates HCC tumorigenesis by targeting PFKP in xenograft tumor models." (PMID 31959898, 2020). "In conclusion, we identified a new candidate oncogenic lncRNA WFDC21P that promotes tumor progression through WFDC21P/Ran/Akt/GSK3β/β-catenin axis and that is positively regulated by transcription factor FOXP3 in GC, which may provide a novel biomarker and therapeutic target for GC." (PMID 34601496, 2021).
cancer (2 papers, 2021 to 2025). A tumor composed of atypical neoplastic, often pleomorphic cells that invade other tissues. "Accordingly, we observed that DCP2 can bind to WFDC21P, a long non-coding RNA, to participate in cancer pathogenesis." (PMID 34301920, 2021). "As a member of the WFDC family, known for roles in immune modulation and cancer, WFDC21P may function as a noncoding regulator, such as a miRNA sponge or scaffold for RNA-protein complexes." (PMID 41424764, 2025). "Additionally, we also found that the expression of WFDC21P in cancer cell lines (A549, H1299, and H1975) was markedly elevated compared with human bronchial epithelial cells (HBE)." (PMID 34301920, 2021).
WFDC21P also shares sentences with these, for which no sentence is quoted: bladder cancer (1 paper); breast carcinoma (1); colon cancer (1); esophageal cancer (1); multiple sclerosis (1); pancreatic cancer (1); rheumatoid arthritis (1).